IL22 (interleukin 22)
Diseases named in the same sentence as IL22 in open-access papers (continued):
Sharing a sentence is not in itself a finding about the gene and the disease.
tumor (continued). "In addition, indolic compounds regulate intestinal homeostasis through induction of IL-22, which improves barrier function, however, in the context of cancer (later stages) IL-22 production can promote tumor progression." (PMID 33916690, 2021). "However, the effects of IL-22 during carcinogenesis are more ambiguous and depend on the tumor entity and microenvironment." (PMID 33851257, 2021). "It has been proved that IL-22 may directly promote tumor growth by engaging STAT3 signaling in tumor cells." (PMID 34941188, 2021). "The impact of IL-22 in cancer is described as both promoting and restraining tumor growth." (PMID 34941188, 2021). "Additionally, in vitro observations proved that IL-22 mainly exerts its pro-tumorigenic effects by enhancing cell proliferation and inhibiting apoptosis of the tumor cells themselves." (PMID 33851257, 2021). "IL-22 was positive in tumor cells, mesenchyme and fibro tissues around cancer nests of LSCC." (PMID 34941188, 2021). "ILC3 produces mainly IL-17 and IL-22, important for mucosal immune responses and tumor progression." (PMID 35008550, 2021). "The expression of IL-22 and associated genes were evaluated by immunohistochemistry and real time polymerase chain reaction in LSCC tissues from 30 patients and adjacent non-tumor tissues." (PMID 34941188, 2021). "Moreover, in an IL-22-free environment mice receiving Il22−/− or Tg × Il22−/− CD4+ T cell showed an equal tumor load, indicating that the observed effect is IL-22 dependent." (PMID 32451418, 2020). "Indeed, we found an increased frequency of IL-17A and IL-22 producing CD4+ T cells in the tumor compared with adjacent normal tissue in patients with CRC." (PMID 32451418, 2020). "Percent of IL-22-positive ILC3 in tumor tissue was higher than that in lymph node (p < 0.05)." (PMID 32649314, 2020). "Tumor cells have been found to display a high level of IL-22 receptor expression as well as increased IL-22 production by surrounding tumor infiltrating T cells, indicating that IL-22 promotes tumor proliferation by engaging the STAT3 signaling in tumor tissues." (PMID 32670290, 2020). "We also analyzed the impact of giving IL-1β and IL-23 on IL-22 levels in tumor tissues." (PMID 32649314, 2020). "Finally, IL-22 has been shown to directly promote tumor growth by inducing proliferation and exhibiting anti-apoptotic effects on tumor cells in the colon and lung." (PMID 32670290, 2020). "Next, we examined whether the reduced tumor growth at 10 weeks of age in IL‐22−/− mice is a consequence of defective mammary gland development due to IL‐22 gene deletion." (PMID 31725949, 2020). "Additionally, we showed that IL‐22 affects the malignant transition of tumor cells through stimulating EMT in cancer cells." (PMID 31725949, 2020). "The analysis of fresh CRC specimens indicated an increased infiltration of CD4+ T cells producing IL-22 by trend compared with adjacent normal colon tissue (frequency of IL-22-producing cells within CD4+ T cells: control: 5.09±5.5 vs tumor: 7.68±6.21, p = 0.0879)." (PMID 32451418, 2020). "An additional possibility is that excised tumors of patients could be confronted with ex vivo–expanded autologous NK cells and exogenous cytokines IL-15, IL-18, IL-22, and IL-23 to reactivate the immune response and establish specific tumor recognition." (PMID 33276556, 2020). "Innate lymphoid cell group 3 (ILC3) is a major producer of IL-22 in 4T1 tumor." (PMID 32649314, 2020). "However, anticancer effects of IL‐22 are also reported in cancer where it attenuates the growth of cancer cells through G2/M cell cycle arrest leading to reduced cell proliferation and tumor weight." (PMID 31725949, 2020). "In summary, IL-22 has dominant performance in CRC carcinogenesis and stemness, pointing that IL-22 identified as an early stage tumour target could be a proper thinking." (PMID 32760201, 2020).
tumor (continued). "In a healthy condition, IL-22 cannot initiate tumor formation by itself and maintains barrier integrity against cancer development; but under inflammatory conditions, IL-22 directly promotes tumor growth or induces “stemness-like” cancer cells via STAT3-dependent signaling." (PMID 32670290, 2020). "Therefore, in the healthy condition, it prevents tumor formation; however, once a tumor has been established, IL-22 promotes tumorigenesis." (PMID 32670290, 2020). "IL-1β and IL-23 increased IL-22 production of ILC3 in the tumor tissue." (PMID 32649314, 2020). "Importantly, both in vivo and in vitro results revealed that miR-181 downregulation reversed the effects of IL22 on CM cell proliferation, migration, invasion, and CM tumor size as well." (PMID 32201538, 2020). "Conversely, data also shows that IL-22 results in tumor progression." (PMID 32670290, 2020). "However, regenerative cell survival signaling of IL-22 has a profound potential to shift toward tumor formation, when over-activated in uncontrolled manner." (PMID 33042126, 2020). "Several lines of evidence have suggested that IL-22 signaling may regulate tumor progression by promoting cell growth and survival." (PMID 31935914, 2020). "In conclusion, IL-22 plays a pro-tumor and anti-apoptosis role in HCC." (PMID 32760208, 2020). "In order to reduce the total amount of transfusion T cells, we used the fourth‐generation CAR‐T cells that could secrete the IL22 cytokine and coincubated them with tumor cells." (PMID 31800160, 2020). "Consistently, IL22 treatment significantly promoted the tumor growth in vivo CM models." (PMID 32201538, 2020). "IL-1β and IL-23 increased percent of IL-22-producing ILC3 in tumor tissue." (PMID 32649314, 2020). "Both tumor-protective and tumor-promoting effects of IL-22 were reported." (PMID 32376911, 2020). "Endogenous IL-22 mRNA level was up-regulated in tumor tissue, compared with normal mammary tissue." (PMID 32649314, 2020). "Moreover, qRT-PCR assay results showed that IL22 treatment indeed increased expression of miR-181 in tumor tissues from CM mice." (PMID 32201538, 2020). "Given the potent pro-tumor value of IL22 and miR-181 in CM, them may serve either as prognostic biomarkers or as potential therapeutic strategies for CM patients." (PMID 32201538, 2020). "Giving exogenous IL-22 increased tumor size and intra-tumor Ki-67-positive cells in vivo." (PMID 32649314, 2020). "Consistent with the idea that IL-22 might also play a role in this process, Il22−/−ApcMin/+ mice develop fewer and smaller tumours than Il22+/+ApcMin/+mice." (PMID 31770366, 2019). "A recent study on human ovarian cancer reported that an ILC3-like population that expresses IFN-γ and IL-22 suppressed the activation and proliferation of tumor-infiltrating lymphocytes (TIL) ex vivo, suggesting a potential benefit of depleting these cells before TIL-based immunotherapy." (PMID 31555301, 2019). "We further show that IL-22 increases DNA damage and genomic instability, which can accelerate cellular transition from heterozygosity (ApcMin/+) to homozygosity (ApcMin/Min) to drive tumour formation." (PMID 31770366, 2019). "Once activated, the ILC3s secret IL-2, which stimulates expansion of tumor-specific lymphocytes; however, since ILC3s also provide an innate source of IL-22 which might favor tumor growth, their role in NSCLC still remains to be identified." (PMID 32039025, 2019). "In this context, IL-17 and IL-22 produced by ILC3 may counteract tumor growth by favoring the recruitment of CD8 T cells, NK cells, and neutrophils." (PMID 32063901, 2019). "Therefore, it seems that IL-22 concentrations are increased in tumour cells and that mice exhibiting reduced concentrations of this cytokine are refractory to CRC development." (PMID 31317039, 2019).
tumor (continued). "ILC2 and ILC3 populations may promote tumor growth and spread through cytokine effects (particularly through IL-33 and IL-22), but they may also promote the formation of tertiary lymphoid structures that promote cytolytic adaptive responses." (PMID 31022866, 2019). "IL-22 functions to regulate the inflammatory conditions of cancer, mediate cancer cell proliferation and migration, and modulate chemotherapeutic drug efficacy by altering the tumor microenvironment." (PMID 31750252, 2019). "IL-22 is now emerging as a cytokine with potent tumor-promoting properties." (PMID 31231372, 2019). "Finally, we showed that IL-22 enhanced tumor growth and induced gefitinib resistance in the PC-9 xenograft model." (PMID 31750252, 2019). "This, in turn, could explain the reduction in tumour numbers in Il22−/−ApcMin/+ compared to Il22+/+ApcMin/+ mice." (PMID 31770366, 2019). "However, in studies of colonic carcinogenesis, Il22−/− mice develop more tumours under inflammation-inducing or mutagenic conditions." (PMID 31770366, 2019). "In addition, the production of IL-22 by NKp46−ILC3 was shown to play a role in tumor maintenance in a bacteria-induced colon cancer model." (PMID 32063901, 2019). "NCR− ILC3-derived IL-22 can act on colon epithelial cells to sustain tumor progression." (PMID 31555301, 2019). "Furthermore, CAFs promote tumor progression through the release of interleukin-1 (IL-1), IL-6, IL-22, and IL-8, of which this latter plays a crucial role in hypoxia-induced tumor apoptosis resistance and EMT remodeling." (PMID 31484464, 2019). "IL22 was reported to promote the malignant transformation of bone marrow-derived mesenchymal stem cells, which exhibit potent tumoritropic migratory properties in tumor treatment." (PMID 31865908, 2019). "This role of IL-22 in inducing proliferation may be detrimental during malignant transformation and tumor progression." (PMID 31311100, 2019). "The serum levels of IL-22 and IL-22-induced CCL20 are increased in patients with MF/SS and are associated with disease severity; this suggests an important role of IL-22 in establishing the tumor microenvironment in MF and SS." (PMID 29915722, 2018). "Our findings are particularly relevant because of the pro-tumor role of IL-17 and IL-22 in MM." (PMID 30719025, 2018). "However, increased IL-22 concentration and RORγt/AhR mRNA relative level was only found in lung-resident tumor site in lung adenocarconoma patients." (PMID 30473538, 2018). "In addition, the expression of other pro-inflammatory cytokines, such as IL-1, IL-6, or IL-22, produced during the tumor-induced inflammatory response, are also likely to be integrated in this network." (PMID 30559930, 2018). "Moreover, a fraction of the MM cell lines and tumours expressed IL-22RA1 and IL-22-induced STAT3 phosphorylation, cell proliferation, and resistance to drug-induced cell death in MM cells." (PMID 29089667, 2017). "Thus, it appears that IL-22 levels are enhanced in tumor tissues and that mice displaying lower levels of this cytokine are protected from tumorigenesis." (PMID 29209314, 2017). "SOCS capability to regulate IL-22-induced pro-tumor responses in transformed keratinocytes is also still unknown." (PMID 28445952, 2017). "Finally, the administration of a SOCS3 mimetic peptide, corresponding to KIR-ESS domain of SOCS3 opposed IL-22 effects in transformed keratinocytes in vitro and counteracted tumor growth in mice." (PMID 28445952, 2017). "IL-22 significantly increased both tumor size and mass compared to the control." (PMID 28445985, 2017). "A tumor proliferating role has been recently shown to be induced by IL-22 in BCC cell lines." (PMID 28829805, 2017). "Notably, the mRNA level of IL-22 was also significantly up-regulated in tumor tissues, and this was confirmed by the results of flow cytometry and ELISA." (PMID 28445985, 2017). "On the other hand, IL-22 activates the STAT3 cascade to enhance tumor generation." (PMID 28271447, 2017).
tumor (continued). "IL-22 has also been reported to endorse tumor cell growth in liver both in vitro and in vivo." (PMID 28050571, 2016). "While technical reasons may be put forward to explain these results, levels of IL-22 may vary significantly between tumor patients." (PMID 27388918, 2016). "In sum, IL-22 seems to promote CRC development via induction of stemness in tumor cells." (PMID 27148488, 2016). "In mice, these IL-22+ lymphocytes were found to augment metastasis as well as HCC tumor growth." (PMID 28050571, 2016). "IL-22 may play a role in controlling tumor growth and tumor progression by inhibiting signaling pathways that promote tumor cell proliferation, such as ERK1/2 and AKT phosphorylation." (PMID 26598081, 2015). "Moreover, IL-22 expression was positively correlated with tumor growth, metastasis and tumor stages." (PMID 25793261, 2015). "However, when we studied its expression in ALCL cell lines, we found expression of IL-22R in five of seven cell lines, suggesting active IL-22 signalling in these tumours." (PMID 25820993, 2015). "Taken together, these results suggest that elevated levels of IL-21 in the tumors of Apcmin/+ mice support a tumor-promoting inflammatory microenvironment characterized by enhanced production of IL-17A, IL-22, TNF-α and IL-6 and hyper-activation of STAT3/NF-kB." (PMID 25839161, 2015). "Indeed, previous studies reported that IL-22 expression is correlated with tumor invasion and poor overall survival in other types of human cancers." (PMID 25793261, 2015). "IL-22 might also play a role during tumor genesis because IL-22 stimulates signaling pathways that are involved in the cell proliferation, cell apoptosis, and cell cycle control." (PMID 24872958, 2014). "The effects of IL-22 on tumor cell proliferation and anti-apoptosis were then investigated." (PMID 23379788, 2013). "Furthermore, up-regulation of IL-22 in TILs derived from human CC was associated with the activation of STAT3 and exhibited tumor promotion and enhancement of metastasis in both in vitro and in vivo model." (PMID 23379788, 2013). "Furthermore, these tumor growth and metastasis promotional effects of IL-22 were demonstrated to occur in a dose-dependent manner when various tumor microenvironments were transplanted with a range of IL-22 levels." (PMID 23379788, 2013). "Therefore, in this study, we introduced a STAT3 activator, IL-22, that exhibits a tumor enhancement mechanism similar to IL-6." (PMID 23379788, 2013). "To further investigate the mechanism of IL-22 on tumor growth, we utilized in vitro studies." (PMID 23379788, 2013). "Conversely, knockdown of IL-22 inhibited tumor progression in a xenograft model of other systems." (PMID 23316374, 2012). "IL-22 may therefore play a role in tumor growth, cell differentiation and progression through STAT3-dependent and -independent pathways." (PMID 22922995, 2012). "Interestingly, in contrast to its protective role in some cells, IL-22 seems to serve as a tumor promoter in other human tumor cells, likely as a result of its regulation of different intracellular signaling pathways in different cell types." (PMID 21625390, 2011). "Our results also showed a tumor growth inhibition effect in vivo when exposure to IL-22." (PMID 21625390, 2011). "In addition to its primary role in modulation of inflammation, IL-22 contributes to tumor cell growth and apoptosis." (PMID 21897855, 2011). "In the current study, we investigated the effects of IL-22, a member of the IL-10 cytokine family, on human RCC cell line A498 cells in vitro and in vivo and studied the possible mechanisms underlying the anti-RCC tumor effects of the cytokine." (PMID 21625390, 2011). "Interestingly, in the context of inflammation-driven cancer models, IL-22 may decelerate tumor growth, but paradoxically, once a tumor is established, it can hasten the progression of cancer." (PMID 40452847, 2025).
tumor (continued). "By using an IL-22 knockout BC mouse model, Katara and collaborators showed that IL-22 knockout led to the arrest of the malignant transition stage through the downregulation of epithelial–mesenchymal transition (EMT)-associated transcription factors and reduced tumor growth." (PMID 40806452, 2025). "In the absence of IL-22BP, IL-22-induced uncontrolled cell proliferation may lead to tumor formation in the repair phase of colitis-associated cancer." (PMID 39630234, 2025). "Therefore, the presence of IL-21 and IL-22 proteins in serum may reflect changes in the tumour microenvironment." (PMID 40729006, 2025). "Additionally, IL-22, which is functionally associated with IL-23R signaling, has been implicated in promoting Sorafenib resistance in HCC through STAT3 activation, leading to enhanced tumor cell survival and decreased apoptosis." (PMID 39921803, 2025). "Similarly, macrophages in metastatic UVM showed strong enrichment for cytokines like Adiponectin, Prolactin, IL7, IL10, IL15, IL9, IL31, APRIL, Persephin, and IL22, highlighting their role in creating a pro-tumorigenic environment through immune modulation and support of tumor growth." (PMID 39916959, 2024). "However, during wound repair in the epithelium, IL-22 promotes tumor development." (PMID 38343544, 2024). "However, IL-5 and IL-22 have not been associated with tumor immunotherapy, and their effects still need to be further studied." (PMID 39003253, 2024). "In certain cases, IL-22 may indeed contribute to tumor cell proliferation, survival, and invasion." (PMID 39195286, 2024). "Furthermore, it has been proposed that high levels of IL-22, IL-10, and CCL20 may determine, as a cascade event, the overexpression of IL-22–STAT3–CCL20–CCR6 thought to be associated with a tumor’s ability to spread to the lymph nodes and internal organs." (PMID 38607023, 2024). "Moreover, IL-22 may contribute to sorafenib resistance of HCC through activating STAT3/CD155 signaling axis to decrease the sensitivities of tumor cells to sorafenib-mediated direct cytotoxicity and NK cell-mediated lysis." (PMID 38596684, 2024). "Current evidence revealed that ILC3s may drive tumor development through IL-17 and IL-22." (PMID 37122757, 2023). "Therefore, the production of IL22 by B cells might be part of a positive feedback loop driving poor prognosis in immunoedited tumours." (PMID 35743743, 2022). "Furthermore, the IL-22 immediately shortened the survival of tumor-bearing mice." (PMID 35669104, 2022). "Moreover, IL-18 also could fine-tune the biological activity of IL-22 via inhibit the production of the IL-22 binding protein, And IL-22 was reported to promote tumor development at later stages." (PMID 36619871, 2022). "This has suggested an ambiguous role for IL22, in which it might provide a protective function in maintaining the mucosal barrier but might be detrimental by contributing to promote tumor growth, a seeming contradiction or ambivalence that warrants further investigation." (PMID 35618586, 2022). "Furthermore, we analyzed the effects of seletalisib on the migration of psoriatic keratinocytes in an in vitro skin injury model, and we found that PI3Kδ inhibition significantly hindered the closure of wounds not only in IL-22-treated keratinocyte cultures but also in untreated cells." (PMID 34685616, 2021). "Elevated levels of IL-23 could be detected likewise in the tumor tissue so that it seems likely that both antigen-presentation and the production of soluble factors such as cytokines contribute to the expansion of IL-22 producing cells in HCC." (PMID 33851257, 2021). "Thus, ILC3 is a predominant producer of IL-22 in tumor tissue of 4T1 model." (PMID 32649314, 2020). "However, we did not observe a significant correlation between the cytokines IL-17F and IL-22 and tumor purity, which may also be due to the low expression level of these cytokines." (PMID 33102239, 2020).